ABCB1 (ATP binding cassette subfamily B member 1)
Diseases named in the same sentence as ABCB1 in open-access papers (continued):
Sharing a sentence is not in itself a finding about the gene and the disease.
cancer (continued). "Since ABCB1 expression in normal tissues leads to higher toxicity in cancer treatment using an ABCB1 inhibitor, researchers have focused on the molecular pathway of MDR cancer cells as a strategy in the development of new molecular targets." (PMID 25401518, 2014). "Taken together, Wnt5A-controlled PKA/β-catenin signaling regulate upregulation of ABCB1, cyclin D1, c-Myc and VEGF in MDR cancer cells for increased survival advantage under chemotherapeutic treatment." (PMID 25401518, 2014). "Sorcin gene is located in chromosome 7, in the same amplicon of other genes involved in the resistance to chemotherapeutic agents in cancer cells (multi-drug resistance, MDR), as the ABC transporters ABCB4 and ABCB1 (Mdr1, or P-glycoprotein 1)." (PMID 25197934, 2014). "Other described targets include ABCG2 (breast cancer-resistance protein, BRCP1) and ABCB1 (P-glycoprotein, MDR1), which were found to be overexpressed in doxorubicin-resistant ATC cancer cells." (PMID 24424445, 2014). "Sorcin is highly expressed in the heart and in the brain, and is overexpressed in many cancer cells, being co-amplified with other proteins involved in the resistance to chemotherapy in cancer cells, as the ABC transporters ABCB4 and ABCB1." (PMID 25197934, 2014). "During the process of studying its anti-cancer properties, curcumin was found to inhibit ATP-binding cassette (ABC) family members including ABCA1, ABCB1, ABCC1, and ABCG2." (PMID 24653706, 2014). "Our investigations indicate that ABCB1 has a role in CRC, particularly in the onset of carcinoma localized in the sigmoid colon." (PMID 25355168, 2014). "Among them, ABCB1, ABCG2 and ABCCs are known as the closest proteins with multidrug resistance in cancer cells." (PMID 23349819, 2013). "Our results showed that U87MG cells acquired resistance to 5-FU through its conversion to cancer stem cells along with upregulation of mdm2 oncogene and ABC transporter genes, ABCB1 and ABCG1." (PMID 24391839, 2013). "An increase in CD24high/CD44low cancer stem cells and upregulation of key ABC transporter genes (ABCG1 and ABCB1) imparted resistance to 5-FU in U87-MCSF cells." (PMID 24391839, 2013). "Inhibition of ABCB1 with XR9576 and cyclosporin A enhanced the cytotoxicity of BI 2536 to ABCB1-overexpressing cancer cells, HCT-15-Pgp, and decreased the IC50 value of BI 2536 by several orders of magnitude." (PMID 23593196, 2013). "As well as to the well-studied multidrug resistant protein P-glycoprotein(ABCB1), the overexpression of ABCG2 results in cancer cells resistant to various chemotherapeutic drugs by extruding these compounds out of the cells, such as topotecan and methotrexate." (PMID 22870247, 2012). "Mechanisms involved in MDR include overexpression of multispecific ATP-dependent drug efflux pumps, such as P-gp (MDR1, ABCB1), MRP1, and BCRP (ABCG2), that reduce the concentration of the drug available for cancer cells." (PMID 22615870, 2012). "Contrary to other cancers, the well-known anti-apoptotic BCL2, the FOS oncogene and the multidrug resistance gene ABCB1 (ATP-binding cassette sub-family B member 1) were down-regulated." (PMID 19662092, 2009). "Despite these limitations, this unique cellular model, which can display HDAC-mediated up- or downregulation of ABCB1 gene according to resistance status, appears therefore useful for effective design of agents to reverse MDR in cancer patients." (PMID 17667922, 2007). "The use of ABCG2 inhibitors and ABCB1 inhibitors, respectively, on ASPC-1 and H2170 cells with high ABCG2 expression and HCT15 cells with high ABCB1 expression can enhance the sensitivity of cancer cells to DXd/SN-38." (PMID 40181988, 2025). "Consequently, modulators of ABCB1 expression, such as HHEX, are promising targets for improving the cytotoxicity of current treatments of ACC and other multidrug resistant cancer type." (PMID 40321776, 2025).
cancer (continued). "During chemotherapy treatment, certain cancer cells upregulate the expression of ATP-binding cassette (ABC) efflux transporters, including P-glycoprotein (P-gp/ABCB1), multidrug resistance protein 2 (MRP2/ABCC2), and breast cancer resistance protein (BCRP/ABCG2)." (PMID 40723808, 2025). "Additionally, it promotes lactate-driven acidification of the tumor microenvironment and induces epigenetic modifications at the ATP-binding cassette sub-family B member 1 (ABCB1) promoter, maintaining cancer stemness and drug efflux capacity." (PMID 40842995, 2025). "Notably, MDR1 (ABCB1, P‐glycoprotein), MRP1 (ABCC1) and BCRP (ABCG2) are major transporters that mediate multidrug resistance in cancer cells by reducing intracellular drug concentrations, thereby diminishing the therapeutic effects of chemotherapeutic agents." (PMID 39877564, 2025). "The authors of both publications concluded that a combined treatment of ABCB1 and ABCG2 substrates with abemaciclib could have a beneficial antitumor effect in multidrug-resistant cancers." (PMID 40284428, 2025). "In addition, compound 64 inhibited the activity of P-glycoprotein (ABCB1), a key player in multidrug resistance in cancer." (PMID 40430417, 2025). "Mechanistic studies dissecting the low-complexity domains and condensate behavior argue for nonidentical roles of YTHDF1 and YTHDF2, while cancer models continue to implicate IGF2BPs in stabilizing drug-resistance transcripts (e.g., ABCB1)." (PMID 41280938, 2025). "In addition to ABCB1, efflux transporters ABCG2 and ABCC1 are also well known for their role in cancer chemoresistance." (PMID 40362377, 2025). "Firstly, QB1561 exhibited remarkable potency in suppressing the proliferation of cancer cells overexpressing ABC transporters, outperforming both the parent drug AF and certain clinically utilized chemotherapeutics that are substrates of ABCB1 or ABCG2." (PMID 40066335, 2025). "Additionally, results for other drug sensitivity markers (ABCG2, ABCB1, BCL2; P < 0.00001) and cancer stem cells (CSCs) markers (ALDH1A1, PROM1; P < 0.01) were also presented." (PMID 40264043, 2025). "The upregulated ABCB1, ZEB1, and CD44 were engaged in microRNA regulation in cancer, SOX2 and KLF4 were engaged in pluripotency of stem cells, and TWIST1 and CD44 contributed to proteoglycans in cancer." (PMID 40251609, 2025). "The ABCB1 (ATP-binding cassette superfamily, subfamily B, member 1) protein, also known as MDR1 (multidrug resistance 1) or P-glycoprotein, was first identified in cultured cancer cells." (PMID 40733143, 2025). "Indeed, NRF2 has lesser-known roles in binding to promoter regions and upregulating expression of the ABCB1 and ABCG2 drug efflux transporters directly impacting drug retention within cancer cells." (PMID 41372143, 2025). "This superfamily is composed of numerous pumps, including P-glycoprotein (also called ABCB1; its expression is detected in many cancers), multidrug resistance proteins (including ABCC1, or multidrug resistance-associated protein 1), and breast cancer resistance protein (BCRP/ABCG2)." (PMID 40869256, 2025). "Although ABCB1 is expressed in a limited number of human normal tissues and at much lower levels than in certain drug-resistant cancers, it is necessary to confirm that ABCB1 inhibition does not affect normal cell functions." (PMID 39003409, 2024). "Clinical trials with ABCB1 inhibitors on cancer patients have not been successful due to low efficacy or adverse effects." (PMID 38163893, 2024). "ATP-binding cassette transporter ABCB1 is known to be involved in drug resistance in cancer treatment, however, current ABCB1 inhibitors have not been successful in clinical trials due to their potential cytotoxicity." (PMID 39003409, 2024). "Notably, EGCG/5-FU treatment has been found to downregulate the expression of multidrug resistance protein 1 (MDR1/ABCB1), a gene responsible for drug efflux and multidrug resistance in cancer cells." (PMID 39000577, 2024).
cancer (continued). "Both ABCB1 and CYP1B1 correlated with microRNAs in cancer and the Nuclear Receptors Meta-Pathway." (PMID 38534761, 2024). "In this report, we demonstrate the feasibility of this unique strategy by designing a derivative of dimeric tryptophan diketopiperazine that displays impressive ABCB1 inhibition against human cancer cells with no obvious toxicity to cells in culture." (PMID 39003409, 2024). "Evidence suggests that a cooperative and potentially compensatory role for ABCB1 and ABCG2 in some cancers, using drugs that can target multiple transporters may provide additional benefits compared to single inhibition." (PMID 38254110, 2024). "The majority of studies on drug efflux ABC proteins, particularly ABCB1 and ABCG2, which are the main ABC transporters frequently overexpressed in multidrug‐resistant (MDR) cancer cells and capable of expelling a variety of xenobiotic substances, have focused on their inhibitors." (PMID 39351597, 2024). "Three major transporters—P-glycoprotein (P-gp or ABCB1), multidrug resistance protein 1 (MRP1 or ABCC1), and breast cancer resistance protein (BCRP or ABCG2) are notoriously involved in therapy resistance in cancer patients." (PMID 38766631, 2024). "Since chemical inhibition of ABCB1 through small molecules is not feasible for cancer therapy due to high toxicity, revealing its regulators offers a good option for reducing its activity." (PMID 38346967, 2024). "Thus, ABCB1, a key player in drug resistance, and NDRG1, a metastasis suppressor in various cancers, were studied as main targets to improve therapy outcomes." (PMID 39457585, 2024). "Understanding the complex role of ABCB1, ABCC1, and ABCG2 in acquired resistance is critical for improving strategies to overcome MDR, increasing treatment efficacy, and ultimately improving outcomes for cancer patients." (PMID 38893104, 2024). "Moreover, high levels of IL-8 correlated with increased levels of drug transport protein ATP-binding cassette subfamily B member 1 (ABCB1), which is a key mediator of chemoresistance through decreasing the intracellular concentration of anti-cancer drugs." (PMID 38562556, 2024). "Additionally, it has been shown to target cancer-related proteins like ABCB1 and P-glycoprotein while also modulating the Akt and Wnt signaling pathways." (PMID 39770038, 2024). "Furmonertinib, a novel third-generation EGFR-TKI, has shown promise in overcoming drug resistance mediated by the ATP-binding cassette transporters ABCB1 and ABCG2, which are central to the development of multidrug resistance in cancer patients receiving conventional chemotherapy." (PMID 39743996, 2024). "Moreover, we discovered that furmonertinib effectively inhibits the drug efflux function of ABCB1 and ABCG2, leading to a substantial restoration of drug-induced apoptosis and reversal of MDR in cancer cells overexpressing these transporters." (PMID 37762275, 2023). "First, we compared the effect of 2 μM HS-173 on cell cycle phase distribution in KB-3-1, KB-V1, S1, and S1-MI-80 cancer cell lines with or without the addition of a reference inhibitor of ABCB1 or ABCG2." (PMID 37048130, 2023). "P-glycoprotein (ABCB1), ABC efflux transporter protein MRP1 (ABCC1), and breast cancer resistance protein (BCRP) (ABCG2), among other drug efflux transporters, have been identified as important mediators of MDR in cancer cells." (PMID 37104009, 2023). "ABCB1 and ABCG2 were first described as mediators of anticancer drug resistance in cancer cells." (PMID 36973040, 2023). "The effect of the tested compound on the efflux ABCB1 activity in 5-FU-sensitive cancer cells (BGC-823) was not obvious." (PMID 36983038, 2023). "METTL3-mediated m6A methylation induces the splicing of estrogen receptor related receptor γ (ERRγ) precursor mRNA, and then ERRγ binds to ATP binding cassette subfamily B member 1 (ABCB1), reinforces its transcription and lowers the sensitivity of cancer cells to numerous anticancer agents." (PMID 37055798, 2023).
cancer (continued). "Drug efflux resistance mechanisms are characterized by the increased expression of ATP-binding cassette (ABC) transporters, such as ABCB1 (P-glycoprotein, MDR-1) or ABCG2 (BCRP), which are able to pump a variety of small molecules out of the cancer cell in an ATP dependent manner." (PMID 37567965, 2023). "Our findings demonstrated that at sub-micromolar concentrations, furmonertinib sensitized multidrug-resistant cancer cells overexpressing ABCB1 or ABCG2, as well as cells with ectopic expression of human ABCB1 or ABCG2, to cytotoxic drugs in a concentration-dependent manner." (PMID 37762275, 2023). "Of these 508 patients, 472 had age data, whereby approximately 97% were over the age of 18, illustrating the lack of knowledge we currently have regarding ABCB1 dysregulation in pediatric cancers." (PMID 37686513, 2023). "Therefore, concurrent use of St John’s wort and anti-cancer agents that are substrates of CYP3A4 and/or ABCB1 can result in a clinically significant pharmacokinetic interaction and unwanted therapeutic outcome." (PMID 36707434, 2023). "Consequently, we investigated the interactions of furmonertinib with ABCB1 and ABCG2 in multidrug-resistant cancer cell lines." (PMID 37762275, 2023). "Our data suggest that furmonertinib was not efficiently effluxed out of cancer cells by ABCB1 and ABCG2." (PMID 37762275, 2023). "At present, no clinically approved inhibitors of ABCB1 or ABCG2 exist for combating multidrug-resistant cancers, primarily due to unexpected adverse drug reactions." (PMID 37762275, 2023). "In addition, miR‐206 targets the 3′‐UTR of mRNA encoding ABCB1, thus, upregulation of FTH1P3 and ABCB1 in paclitaxel‐resistant cancer cells derived from TBNC suggested FTH1P3 targets miR‐206, thereby freeing ABCB1 expression." (PMID 37795578, 2023). "P-glycoprotein (P-gp, ABCB1) transports structurally dissimilar hydrophobic and amphipathic compounds, including anticancer drugs, thus contributing to multidrug-resistant cancer." (PMID 37444569, 2023). "Consequently, patients with high ABCB1- or ABCG2-expressing multidrug-resistant tumors are usually insensitive to chemotherapy, resulting in cancer relapse and treatment failure." (PMID 37048130, 2023). "In this study, we found that neither ABCB1 nor ABCG2 confers significant resistance to furmonertinib in cancer cells." (PMID 37762275, 2023). "ABCB1, a member of the ABC family, is a transmembrane transporter that pumps drugs out of cells, reducing their effective concentration and increasing the drug resistance of cancer cells." (PMID 38125763, 2023). "P-glycoprotein (P-gp/ABCB1) is an ATP-binding cassette (ABC) transporter that extrudes various anticancer drugs (e.g., paclitaxel, etoposide, vincristine, and doxorubicin) from cancer cells, as well as various endogenous molecules." (PMID 35450042, 2022). "MRTX849 also had no change on predominantly cell membrane localization of ABCB1 in the MDR cancer cell lines." (PMID 36104708, 2022). "Overall, systemic effects pose the biggest challenge in targeting overexpressed ABCB1 in PCa cells since all three examined approaches are not specific to ABCB1-expressing cancer cells." (PMID 36614114, 2022). "The influence of ABC pumps in anthracycline pharmacokinetics has been suggested in vitro and studies in other cancers, but a population pharmacokinetic study performed in AML failed to reproduce these findings with ABCB1 and ABCG2 polymorphisms." (PMID 35456712, 2022). "We found that hydroxygenkwanin is equally cytotoxic to both parental and multidrug-resistant cell lines, thus suggesting that it is not rapidly transported out of cancer cells by either ABCB1 or ABCG2." (PMID 36361555, 2022). "Nilotinib, a second-generation of TKI, also inhibited the efflux function of ABCB1, ABCG2, and ABCC10 in cancer cells, thereby increasing the intracellular concentrations of the chemotherapeutic agents (e.g., PTX and doxorubicin) and potentiating their cytotoxic effects both in vitro and in vivo." (PMID 35327403, 2022).
cancer (continued). "ABCB1, also known as MDR1 or P-glycoprotein (P-gp), is an ATP-binding cassette transporter functioning as an efflux pump, which lowers the intracellular accumulation of various anti-cancer drugs." (PMID 36233525, 2022). "FOXC1 knockout followed by RNA-seq revealed that FOXC1 positively regulates many of the same genes that are overexpressed in SP cells, some of which (e.g., ABCB1 and ID3) have been shown to play a role in drug resistance and cancer stemness in previous reports." (PMID 35406487, 2022). "Additionally, it was found that ARS-1620 remarkably stimulated ATPase activity of ABCB1, and the HPLC drug accumulation assay displayed that ARS-1620 was actively transported out of ABCB1-overexpressing cancer cells." (PMID 35281897, 2022). "Due to the decreased ABCB1 transporter expression, cdk6-deficient KB-C2 cells achieved remarkable reversal of MDR, showing significant increase in sensitivity to ABCB1 substrates colchicine and paclitaxel, demonstrating that CDK6 regulates cancer MDR mediated by ABCB1 specifically." (PMID 35459184, 2022). "MDR phenotype; P-glycoprotein; ABCB1; Cancer biomarkers; ABC transporters." (PMID 36325145, 2022). "The significant contribution of thethree major ABC transporters, including ABCB1 (P-glycoprotein/P-gp/MDR1), ABCG2 (Breast Cancer Resistance Protein/BCRP/MXR), and ABCC1 (Multidrug Resistance Protein 1/MRP1) to MDR in cancer chemotherapy is well documented in vitro studies." (PMID 36104708, 2022). "As expected, no apoptosis was found in ABCB1-overexpressing cancer cells treated with PTX, Dox, or BGJ 398 alone." (PMID 35327403, 2022). "Overall the obtained results from this study suggest that 1,2,5-trisubstituted benzimidazoles possibly are promising candidates for further optimisation and development of potential anticancer agents with ABCB1 inhibitory activity and therefore overcome MDR in cancer cells." (PMID 36168121, 2022). "To delineate between these possibilities, we initially compared the expression of MDR-related proteins between non-treated vs. BGJ 398-treated ABCB1-overexpressing cancer cells." (PMID 35327403, 2022). "Similar to its functional homologues ABCB1 and ABCC1, ABCG2 also has a notorious function in extruding antitumor drugs from various cancer cells, which can result in multidrug resistance, a severe obstacle in cancer treatment." (PMID 36294746, 2022). "The overexpression of MDR-ABC transporters genes such as ABCB1, ABCG2, and ABCC2 has been reported to lead to interindividual difference in bioavailability of drugs, and it represents a potential mechanism of primary resistance to anti-cancer agents." (PMID 34055641, 2021). "In summary, as shown in schematic illustration, our study revealed the effect of ABCB1 and ABCG2 on the pharmacological impact of citarinostat, which may play an important role in the development of resistance to citarinostat in cancer cells." (PMID 33807514, 2021). "In this study, we found that rutaecarpine, at a non-toxic concentration, significantly sensitized ABCB1-overexpressing cancer cells to their substrates, respectively, in a dose-dependent manner." (PMID 34572328, 2021). "To examine the effect of ABCB1 and ABCG2 on the chemosensitivity of human cancer cell lines to citarinostat, we determined the cytotoxicity of citarinostat in multiple pairs of ABCB1- or ABCG2-overexpressing multidrug-resistant cancer cell lines and the respective drug-sensitive parental lines." (PMID 33807514, 2021). "However, we found that citarinostat had a significantly reduced effect on HDAC6 in ABCB1-overexpressing KB-V-1 and ABCG2-overexpressing S1-M1-80 cancer cells as compared to the respective parental KB-3-1 and S1 cancer cells." (PMID 33807514, 2021). "Since gedatolisib had limit effect to inhibit ABCB1- and ABCG2-overexpression cancer cells, the potential mechanisms could be related with the upregulation of ABC transporter expression level." (PMID 33593355, 2021).